LIPN (lipase family member N)
Description:
Plays a highly specific role in the last step of keratinocyte differentiation. Contains two distinct domains: the alpha/beta hydrolase fold and the abhydrolase-associated lipase region, also features the consensus sequence of the active site of a genuine lipase. May have an essential function in lipid metabolism of the most differentiated epidermal layers.
Synonyms: LIPL4; bA186O14.3; ARCI8; LI4
Tractability: Small molecule: it belongs to a druggable protein family. Antibody: UniProt places it where antibodies can reach, with high confidence; its Gene Ontology location is reachable by antibodies, with high confidence; UniProt predicts a signal peptide or a membrane-spanning region.
Gene: Protein-coding gene on chromosome 10 (88,759,982 to 88,779,626, forward strand). Ensembl gene ENSG00000204020.
Subcellular location: Secreted
Pathways (Reactome):
Developmental Biology: Formation of the cornified envelope
Gene Ontology:
Molecular function: lipoprotein lipase activity; carboxylic ester hydrolase activity; hydrolase activity, acting on ester bonds; lipase activity; sterol ester esterase activity; triacylglycerol lipase activity
Biological process: cornification; lipid metabolic process
Cellular component: extracellular region
Genetic constraint (gnomAD): Loss-of-function variants: 13 observed, 19.27 expected, observed/expected ratio (o/e) 0.67, 90% interval 0.44 to 1.07. The upper end of that interval is the gene's LOEUF score, 1.07, which puts it in group 4 of 6, group 1 being the genes least tolerant of losing a copy. Missense variants: 267 observed, 270.21 expected, observed/expected ratio (o/e) 0.99, 90% interval 0.89 to 1.09. Synonymous variants: 88 observed, 91.73 expected, observed/expected ratio (o/e) 0.96, 90% interval 0.81 to 1.14.
Homologues: Orthologues: chimpanzee LIPN (99% identical), macaque LIPN (97% identical), rabbit LIPN (86% identical), pig LIPN (83% identical), dog LIPN (82% identical), mouse Lipn (82% identical), rat Lipn (82% identical), guinea pig LIPN (82% identical), Caenorhabditis elegans lipl-1 (37% identical), Caenorhabditis elegans lipl-5 (37% identical), Caenorhabditis elegans lipl-3 (37% identical), Caenorhabditis elegans lipl-2 (37% identical), and 24 more. Paralogues in human: LIPA (53% identical), LIPM (52% identical), LIPF (51% identical), LIPK (50% identical), LIPJ (45% identical).
Diseases named in the same sentence as LIPN in open-access papers:
LIPN is named in the same sentence as 19 diseases in open-access papers, as found by Europe PMC text mining. Sharing a sentence is not in itself a finding about the gene and the disease. The quoted sentences say what the papers report.
amoebiasis (1 paper, 2023). "The expression of LIPN was associated with an up-regulated pathway of amoebiasis, Autophagy-animal, Rheumatoid arthritis, and so on." (PMID 36979470, 2023). "The expression of LIPN was associated with the up-regulated pathway of amoebiasis, Autophagy-animal, Legionellosis, Longevity regulating pathway, Longevity regulating pathway-multiple species, Malaria, Pantothenate and CoA biosynthesis, Renal cell carcinoma, Rheumatoid arthritis, and Ribosome." (PMID 36979470, 2023).
gestational diabetes mellitus (1 paper, 2023). "In another paper, gestational diabetes mellitus was associated with lipolysis-related genes such as LIPN." (PMID 36979470, 2023).
Primary immunodeficiency (1 paper, 2023). "The expression of LIPN was associated with a down-regulated pathway of aminoacyl-tRNA biosynthesis, Primary immunodeficiency, DNA replication, and so on." (PMID 36979470, 2023).
infection (2 papers, 2020 to 2025). The state of being infected such as from the introduction of a foreign agent such as serum, vaccine, antigenic substance or organism. "Similar to other vaccine candidates (lipN mutant), PAN-based vaccines were able to significantly lower M. paratuberculosis levels in the liver, spleen and lymph nodes but did not prevent dissemination of infection." (PMID 32128256, 2020).
LIPN also shares sentences with these, for which no sentence is quoted: ichthyosis (3 papers); autosomal recessive congenital ichthyosis (2); gynecologic diseases (1); hypertrophic cardiomyopathy (1); intestinal disease (1); legionellosis (1); malaria (1); Menstrual disorder (1); peripheral neuropathy (1); renal cell carcinoma (1); rheumatoid arthritis (1); Sepsis (1); staphylococcus aureus infection (1); systemic lupus erythematosus (1); Vertigo (1).